FABP1 (fatty acid binding protein 1)
Diseases named in the same sentence as FABP1 in open-access papers (continued):
Sharing a sentence is not in itself a finding about the gene and the disease.
Obesity (continued). "FABP1 is probably increased by compensatory mechanisms in response to HFD consumption, and this compensation may contribute to the development of obesity; thus, we postulate that NTS deficiency inhibits the compensatory effects and, in so doing, attenuates the associated condition of obesity." (PMID 40451927, 2025). "Liver-type FABP (L-FABP or FABP1) is the predominant isoform in PTCs, which has been shown to promote lipid accumulation in obesity-related CKD." (PMID 39765868, 2024). "In addition, a previous review suggested that FABP1 may play an important role in preventing age- or diet-induced obesity 38, and thus that the ''paradoxical'' elevation of serum FABP1 in obese subjects may be compensatory up-regulation to counteract the metabolic stress imposed by obesity." (PMID 32038102, 2020). "FABP-1 is relatively over-expressed in patients with simple steatosis compared with those with obesity; however, throughout the NAFLD stages, it was observed that FABP-1 was significantly under-expressed in patients with mild and progressive NASH." (PMID 26999105, 2016). "FABP1 has been shown to be elevated in several metabolic diseases, such as MASLD, obesity, and diabetes, suggesting that it may be a marker or pathogenic factor for these diseases." (PMID 38791126, 2024). "Of note, the ALA diet-dependent up-regulation of fatty acid-binding protein 1 (FABP1; L-FABP) was reported in the small intestine of the C57BL/KsJ-db/dg obesity mouse model, demonstrating a direct influence of this essential fatty acid on the regulation of host metabolism." (PMID 32168729, 2020). "In accordance with previous reports, our results showed increased levels of FABP-1 in patients with obesity and diabetes with or without fatty infiltration." (PMID 32933141, 2020). "One gene (fatty acid binding protein 1, FABP1) was dysregulated in all three models of mammalian obesity, but was not spotted in the zebrafish microarray." (PMID 20961460, 2010).
acute kidney injury (49 papers, 2013 to 2025). Sudden and sustained deterioration of the kidney function characterized by decreased glomerular filtration rate, increased serum creatinine or oliguria. "Elevated circulating FABP1 is associated with severe abdominal injury and acute renal failure in trauma subjects." (PMID 35682894, 2022). "FABP1 has been suggested as a marker of renal failure, FABP3 as a marker of myocardial infarction, and FABP5 has lately been debated as a diagnostic marker for Sjögren’s syndrome." (PMID 32272779, 2020). "Consistent with the transcriptomic data of a study on young and aged human kidneys we found apolipoprotein E and Fabp1, a potential marker of acute kidney injury, to be increased in aged kidney samples pointing to a conserved aging mechanism." (PMID 26886165, 2016). "Importantly, FABP1 has a protective role in acute kidney injury (AKI) and chronic kidney disease (CKD) 14, and can decrease glomerular injury at the early stage of IgAN in animal experiments." (PMID 36147466, 2022).
diabetes (33 papers, 2011 to 2026). "The fact that a significant association between FABP-1 staining PaC and PaC with diabetes was found suggests that the true association is stronger." (PMID 21251264, 2011). "Further studies with closely phenotyped patient samples are required to understand the true relationship between FABP-1, PaC and PaC-associated diabetes." (PMID 21251264, 2011). "The primary aim of this pilot study was to experimentally validate the predicted association between FABP-1 with PaC and PaC with diabetes." (PMID 21251264, 2011). "The primary aim of this pilot study was to experimentally validate the predicted association between FABP-1 and PaC and PaC with diabetes." (PMID 21251264, 2011). "Using methods in integrative genomics, we predicted an association between FABP-1 and pancreatic adenocarcinoma and pancreatic adenocarcinoma with diabetes." (PMID 21251264, 2011). "The association of FABP-1 with pancreatic adenocarcinoma and diabetes is of interest." (PMID 21251264, 2011). "With its up-regulation in various forms of cancer and effects on metabolism, it is plausible that FABP-1 could be a biomarker for pancreatic cancer and pancreatic cancer-associated diabetes." (PMID 21251264, 2011). "It has been reported that the FABP1 liver level represents a diagnostic marker in NAFLD, and circulating FABP1 have been found to be higher in type 2 diabetes mellitus patients with NAFLD." (PMID 36770927, 2023). "Since hyperuricemia and FABP1 are closely related to diabetes and liver-related metabolic disorders, we first assessed the correlation between serum FABP1 or UA levels with glucose metabolism and liver enzyme indices in the NUA and HUA groups." (PMID 36277716, 2022). "Currently, FABP1 is commonly used as a specific biomarker for liver disease and type 1 diabetes mellitus in clinical practice." (PMID 36277716, 2022). "In this study, we investigated the association between plasma FABP1 levels and NAFLD in patients with type 2 diabetes mellitus (T2DM)." (PMID 32038102, 2020). "Compared to normal controls, we found a significant positive association between increased FABP-1 staining and PaC on FFPE-TMA, strengthened by the presence of diabetes." (PMID 21251264, 2011). "Two genes with variants leading to Maturity Onset Diabetes of the Young (MODY), Hepatic nuclear factor (HNF)-4alpha and HNF-1alpha, are known to directly bind to the promoter region of FABP-1." (PMID 21251264, 2011). "Compared to normal controls, there was a significant positive association between FABP-1 staining and PaC on FFPE-TMA, strengthened by the presence of diabetes." (PMID 21251264, 2011). "Studies have shown that FABP1 is closely related to the occurrence and development of diabetes." (PMID 37740216, 2023). "Plausibility of FABP-1 as a biomarker for diabetes comes from animal and human data." (PMID 21251264, 2011). "Our data showed increased cholesterol uptake genes (FABP1, CD36, and SRA1) in diabetes, which was in an agreement with recently published studies." (PMID 36829889, 2023). "There were no significant statistical differences in sex, blood pressure, hypertension, diabetes, dyslipidemia, coronary artery disease, stroke, and blood lipid levels in both FABP2 and FABP1 genotypes." (PMID 37091779, 2023). "The patients with G3a-G4 had higher cardiovascular disease, oral hypoglycemic agent rates (OHA), age, diabetes duration, uric acid, estimated GFR, UACR, FABP1, and FABP3 than those with G1 and G2." (PMID 34975301, 2022). "The mRNA expression levels of FAT/CD36, FABP1, and FATP5 in diabetes group were higher than those in control group." (PMID 23691525, 2013). "In the present study, the mRNA expression levels of FABP1 and FAFP5 were increased in diabetic group, which is consistent with the previous report that the expression of FABP is increased in STZ-induced diabetes." (PMID 23691525, 2013).
diabetes (continued). "Because the data failed to meet assumptions of normality and homogeneity of variances, we performed nonparametric Kruskal-Wallis ANOVA to compare FABP-1 staining in normal, PaC without DM (PaC no DM), and PaC with diabetes (PaC-DM) samples." (PMID 21251264, 2011).
steatosis (31 papers, 2008 to 2025). Increased lipid within the cytoplasm of cells. "FABP1 silencing in the liver has been reported to cause decrease in steatosis, inflammation, and oxidative stress." (PMID 38564126, 2024). "Notably, hepatic fatty acid binding protein 1 (FABP1) was increased concomitantly to increased steatosis in STAT6 deficiency." (PMID 41409600, 2025). "FABP1 plays a key role in the uptake and transport of fatty acid and in steatosis development, while GK is directly involved in TG synthesis." (PMID 36770927, 2023). "Further, PGAM5 knockout ameliorates palmitate-induced steatosis and reduces expression of FABP1 in HepG2 and Huh7 cell lines." (PMID 37835490, 2023). "Our findings suggest that direct activation of GLP-1R by Ex-4 reduces OA-induced steatosis in HepG2 cells by reducing fatty acid uptake and transport via FABP1 downregulation." (PMID 35140289, 2022). "To better understand the potential role of β-catenin as a molecular determinant through which Ex-4 mediates its beneficial effect on steatosis, we quantified the expression of FABP1, FOXA1, and ApoB after β-catenin silencing." (PMID 35140289, 2022). "Additionally, the double KO (Fabp1/Mttp DKO) exhibited reduced steatosis and fibrosis compared to the Mttp-KO mice." (PMID 39049993, 2024). "Not only did the donor microbiota from patients with steatosis trigger hepatic TG accumulation in recipient mice but it also affected the hepatic transcriptome, through an increased expression of genes involved in lipid metabolism such as FABP1." (PMID 33477939, 2021). "Additionally, FABP1 was considered an early biomarker that determines the extent of fatty liver infiltration in NAFLD patients through increasing steatosis and subsequent activation of the hepatic stellate cells." (PMID 34306045, 2021). "FABP1 suppression has been correlated to the reduction of steatosis, inflammation and oxidative stress, suggesting that FABP1 downregulation may slow down the progression of NAFLD into NASH." (PMID 33348908, 2020). "Therefore, one explanation for the Ex-4-induced improvement in steatosis observed in our model could be a decreased fatty acid uptake by FABP1." (PMID 35140289, 2022). "In detail, we found the down expression of FABP1 (40 times) and APOC3 (11.98 times), PPARGC1A and GK (11 times), ABCA1 and SRBF2 (3 times) compared to the steatosis control." (PMID 36770927, 2023). "Hence, the increased activity of FABP1 and the resulting enhanced intracellular trafficking of fatty acids in dyslipidemic condition may be shunting more detrimental fatty acids to storage and thereby promoting steatosis and NASH." (PMID 32933141, 2020). "MiR‐4672 prevents hepatocyte steatosis and injury by directly targeting the 3′ UTR region of FABP1." (PMID 40223182, 2025). "In our experiments, the downregulation of genes involved in lipid/cholesterol metabolism and transport (such as FABP1, APOC3, PPARGC1A, GK, ABCA1, and SRBF2) induced by curcumin treatment could explain the observed reduction of steatosis and lipid content." (PMID 36770927, 2023). "Interestingly, FABP1 was overexpressed in our study in NAFLR mice, suggesting similar mechanisms linking the microbiota to steatosis in the two studies." (PMID 33477939, 2021). "The treatment with curcumin-andrographolide in association maintained the ability to regulate in a negative manner FABP1 (15.96 times), PPARGC1A (7.85 times), GK and ABCA1 (4 times), and APOC3 (2.04 times) in respect to the steatosis control." (PMID 36770927, 2023).
chronic kidney disease (21 papers, 2015 to 2026). Impairment of the renal function secondary to chronic kidney damage persisting for three or more months. "Importantly, FABP1 has a protective effect in acute kidney injury and chronic kidney disease and may reduce glomerular injury in the early stages of IgAN." (PMID 38925330, 2024). "There is increasing evidence that FABP1 and FABP 2 play a role in the development and progression of chronic kidney disease." (PMID 32922199, 2020).
hepatocellular carcinoma (21 papers, 2004 to 2025). A malignant tumor that arises from hepatocytes. "In hepatocellular carcinomas, reduced FABP1 expression was linked to advanced stage (p = 0.0002), presence of lymph node metastasis (p = 0.0042), and female gender (p = 0.0002)." (PMID 35951102, 2022). "Finally, the high expression of FABP1 in hepatocellular carcinoma was associated with a better prognosis than in patients with low FABP1 expression." (PMID 31143113, 2019). "Orlistat, a FABP1 inhibitor, limits tumor growth in hepatocellular carcinoma while enhancing anti-PD-1 function." (PMID 40694956, 2025). "Several studies have shown that FABP1 expression is highly specific to tumours and is predominantly found in hepatocellular carcinomas (HCCs), colorectal carcinomas, and other gastrointestinal adenocarcinomas." (PMID 41149452, 2025). "FABP1 is highly expressed in hepatocellular carcinoma and is proposed to promote angiogenesis, tumorigenesis, and metastasis through VEGFR2/SRC proto-oncogene tyrosine-protein kinase signaling and the focal adhesion kinase/cell division cycle 42 pathway." (PMID 37207357, 2023). "In summary, our data show that FABP1 expression has high tumor specificity and preferentially occurs in hepatocellular carcinomas, colorectal carcinomas, mucinous ovarian cancer, and other gastrointestinal adenocarcinomas." (PMID 35951102, 2022). "HBx can also increase the expression of liver fatty acid binding protein 1 (FABP1), a key driver gene of lipid accumulation in hepatoma cells, which level was enhanced in the sera of HBV-infected patients and the sera and liver of HBV transgenic mice." (PMID 36466918, 2022). "For example, FABP1 enhances mitochondrial β-oxidation in hepatocellular carcinoma to provide energy, while FABP4 promotes breast cancer cells to take up fatty acids from adipocytes and activates the STAT3 pathway to drive epithelial-mesenchymal transition (EMT)." (PMID 40717587, 2025). "PGAM5’s role in hepatocellular carcinoma includes regulation of fatty acid metabolism, which may be related to expression of the fatty acid transporter, FABP1." (PMID 37835490, 2023). "Our data suggest that PGAM5’s role in hepatocellular carcinoma includes regulation of fatty acid metabolism, which may be implemented through expression of the fatty acid transporter, FABP1." (PMID 37835490, 2023). "The highest FABP1 positivity rates were seen in colorectal adenomas (86%), in colorectal adenocarcinomas (71.1%), and in hepatocellular carcinomas (65.3%), followed by mucinous carcinoma of the ovary (34.6%), cholangiocarcinoma (21.6%), and various adenocarcinomas from the digestive tract (10–23%)." (PMID 35951102, 2022). "It is reported that down-regulation of FABP1 expression, significantly associated with poor differentiation and high expression of β-catenin and glutamine synthetase (GS), caused phenotypic changes during tumor progression in almost 10% of hepatocellular carcinoma (HCC)." (PMID 30992015, 2019). "In hepatocellular carcinoma (HCC), the upregulated fatty acid-binding protein 1 (FABP1) interacts with the VEGF receptor and Src via the focal adhesion kinase (FAK) and enhances the expression of the angiogenic vascular endothelial growth factor A (VEGF-A)." (PMID 34685761, 2021). "HBV is a small hepatotropic DNA virus responsible for some chronic liver diseases in humans and the expression level of liver fatty acid binding protein 1 (FABP1), a key regulator of hepatic lipid metabolism, was elevated in HBV-producing hepatoma cells." (PMID 34072178, 2021). "However, our data show that 50–70% of advanced and metastatic hepatocellular carcinomas and up to 20% of low-stage and grade carcinomas may be FABP1 negative." (PMID 35951102, 2022).
type 2 diabetes (21 papers, 2011 to 2025). "One single nucleotide polymorphism of the FABP-1 gene, rs2197076 and one haplotype were associated with an increased risk of type 2 diabetes even when adjusted for age, sex and BMI." (PMID 22396741, 2012). "The main objective was to evaluate the association between SNPs and haplotypes of the FABP1-4 genes and type 2 diabetes, as well as its interaction with fat intake, in one general Spanish population." (PMID 22396741, 2012). "The study supports the role of common variants of the FABP-1 gene in the development of type 2 diabetes in Caucasians." (PMID 22396741, 2012). "One polymorphism of the FABP1 gene was strongly associated with the risk of type 2 diabetes in Hortega population even when Bonferroni test was applied for multiple comparisons." (PMID 22396741, 2012). "Two studies of type 1 diabetes 39,40 and three studies of type 2 diabetes 41-43 reported on the relationship between urinary FABP1 concentrations and the severity of diabetic nephropathy." (PMID 32038102, 2020). "Urinary FABP1 accurately reflected the severity of diabetic nephropathy in type 2 diabetes." (PMID 23144966, 2012).
kidney damage (20 papers, 2016 to 2025). "Previous studies have associated FABP1 with nonalcoholic fatty liver disease and nephropathy in patients with T2D, effectively underscoring its potential as a biomarker for metabolic dysfunction." (PMID 37792298, 2023). "Fatty acid binding protein-1 (FABP1) is expressed in renal proximal tubule cells and is released into the urine in response to hypoxia caused by decreased peritubular capillary blood flow, serving as an early marker of kidney damage." (PMID 41155635, 2025). "Elevated plasma levels of the kidney marker KIM-1, the liver marker α-GST, and the kidney and liver marker FABP-1 in AIP cases suggest proximal tubular kidney damage and hepatocellular damage." (PMID 38276268, 2023). "The aim of this study was to investigate the relation of circulating FABP1 and FABP2 levels to nephropathy in patients with T2DM." (PMID 32922199, 2020). "The purpose of the present study was to investigate the levels of FABP1 and FABP2 in T2DM patients in various stages of nephropathy to clarify the role of FABP1 and FABP2 in the pathogenesis of diabetic nephropathy." (PMID 32922199, 2020). "The results of this study suggest that endotoxin and FABP2/I-FABP may be used for indicating intestinal damage, creatinine for kidney damage, and AST and FABP1/L-FABP for liver damage during the post-REBOA phase." (PMID 34211011, 2021). "The mean FABP1 and FABP2 levels increased parallel to the severity of nephropathy." (PMID 32922199, 2020).